IL6 (interleukin 6)
Diseases named in the same sentence as IL6 in open-access papers (continued):
Sharing a sentence is not in itself a finding about the gene and the disease.
infection (continued). "As the inflammatory response continues, monocytes and macrophages are recruited to assist and IL-6 is an important regulator in this transition, ensuring that inflammation is sufficient to continue mounting an adequate response to a persisting infection." (PMID 37535121, 2023). "Levels of IL-6, TNFα, IL-10, and other cytokines are significantly increased with infection; elevation of IL-6 and IL-10 is a reliable indicator of a more severe disease." (PMID 36771194, 2023). "Infection-related biomarkers such as IL-6 and CRP are widely used to predict disease progression and prognosis." (PMID 37894092, 2023). "IL-6, another cytokine of the acute inflammatory response, is also broadly crucial in restricting infections and is strongly induced during GAS infection (4, –, 6)." (PMID 37874162, 2023). "In agreement with our in vitro and intraperitoneal infection data, ΔEhaF-infection induced significantly higher levels of IFNβ and IL-6 in the colon compared to wild-type EHEC infection." (PMID 37041208, 2023). "CRP is a protein composed of five subunits synthesized by the liver which reacts to the acute phase of an inflammatory/infection process, mainly due to the action of IL-6 on the gene that controls CRP transcription." (PMID 37111388, 2023). "Given that the ACE2 receptor is expressed in the sustentacular cells and glandular cells of the olfactory epithelium; inflammation and cytokine release (such as IL-6) upon infection alters neuronal signalling, leading to anosmia." (PMID 37112923, 2023). "Some studies described increased levels of IL-6 after infection with virulent genotype II ASFV isolates, alongside other pro-inflammatory cytokines, with peaks at the end of the observation period at day 7 pi." (PMID 36680273, 2023). "Myeloid DCs were present at very low frequencies (<2%), and not more than 70 total cells were detected to be harboring mRNA from TNF, IL6 or IL10 after infection." (PMID 37024448, 2023). "TNF‐α is a pluripotent and proinflammatory cytokine produced by activated macrophages, and TNF‐α induces the production of other cytokines, such as IL‐6, during infection, thereby increasing leukocyte accumulation and amplifying the inflammatory cascade." (PMID 37644785, 2023). "In the present study, we show the critical role of IL-6 in the neurotropic infections induced by WNV or JEV in human neuronal cells, primary murine cells, and mice." (PMID 38053527, 2023). "The secretion of cytokines IL-1 α, IL-6 and IL-8 was measured after 48 h of infection with C. acnes and S. epidermidis in human primary sebocytes (same model as before)." (PMID 36838382, 2023). "This buffering is overcome when IL-6 concentration strongly increases during infection or inflammation, and reaches – together with sIL-6R – molar concentrations similar to sgp130." (PMID 36810097, 2023). "This can lead to unresolved chronic inflammation in PCS patients, with elevated levels of C-X-C motif chemokine ligand 10 (CXCL10), interleukin-6 (IL-6), and D-dimer even months after the acute phase of infection." (PMID 37507580, 2023). "This was also demonstrated in an experiment with mouse hepatocytes, where infection of hepatic epithelial cells resulted in significant increases in pro-inflammatory and chemokines such as IL-6, RANTES, IP-10, and MIP-3a." (PMID 37112920, 2023). "IL-6, categorized as a proinflammatory cytokine, plays a crucial role in the immune system’s response to a range of stimuli such as infections, injuries, and various diseases." (PMID 37986183, 2023). "During early infection, TNFα, IL-1α, IL-6 and IL-8 are produced and result in stimulation of local and systematic pro/anti-inflammatory responses." (PMID 36726139, 2023). "Historically, studies have posited that Coprococcus can modulate the production of cytokines IL-1β and IL-6, thereby orchestrating the inflammatory response during an infection." (PMID 37781358, 2023).
infection (continued). "We observed that neuronal cultures derived from IL-6−/− mice exhibited significantly higher virus titers upon WNV NY99 or WNV Eg101 infection than those from WT mice." (PMID 38053527, 2023). "The data suggest that early after infection, high levels of IL-6 exert an antioxidative effect on inflammatory monocytes." (PMID 37818368, 2023). "IL-6 measurements increased following dual-infection as compared to S. maltophilia single-species infection, with a significant increase following dual-infection between CF and WT groups (***P<0.001)." (PMID 36748431, 2023). "IL6 in SP has been studied extensively and shows strong potential as a biomarker for genital tract inflammation and/or infection, and disease." (PMID 36891953, 2023). "Inflammatory cytokines TNF-α and IL-6 are swiftly and transiently produced in response to infection and tissue injury." (PMID 38138520, 2023). "Regarding the inflammatory cytokines, including G-CSF, GM-CSF, TNF-α, IL-1b, IL-6, and IL-17, the HD patients in the breakthrough infection group had higher TNF-α and IL-6 levels than those in the booster immunization group (p = 0.017 and 0.039, respectively)." (PMID 37515030, 2023). "We further analyzed the active status of infiltrated immune cells during infection by measuring the levels of pro-inflammatory markers such as IFNγ, TNFα, and IL-6 in the lungs by Western blotting." (PMID 36676177, 2023). "Meanwhile, Th2 cells mainly respond to the infection of extracellular bacteria, fungi, and parasites, by secreting IL-4, IL-6, and IL-10." (PMID 37357919, 2023). "Our data show that IL-6 represents a suitable early infection marker for laboratory screening in suspected cases of neonatal EOS, given its detectable early rise." (PMID 38255366, 2023). "Cytokines Tnfa and Il6 mRNA levels were clearly lower in the kidney of p38γ/δKIKO mice than in WT animals at day 3 post-infection." (PMID 37458356, 2023). "Collectively, these results suggest that infection with ΔrelAΔspoT EPEC can induce IL-6 expression both in vitro and in vivo." (PMID 36937293, 2023). "As a primary link of immune responses, AMs and DCs play an important role in recruiting cells to the infection site with the secretion of IL-1 and IL-6." (PMID 37686061, 2023). "According to our results, SARS-CoV-2 infection at delivery is related to higher concentrations of IL-6 in umbilical cord blood, even if the infection is asymptomatic." (PMID 37685739, 2023). "These cells rapidly respond to infections by secreting inflammatory cytokines [IL-6, IL-12, tumour necrosis factor-alpha (TNF-α) and IL-1β] to repair damaged tissue." (PMID 36601859, 2023). "CRP acts as an acute phase plasma protein in response to inflammation or infection; it is regulated by proinflammatory cytokine stimulation such as tumor necrosis factor-alpha, interleukin-1 (IL-1), and IL-6." (PMID 36674837, 2023). "In a mouse model infected with Pseudomonas, the intrapulmonary levels of inflammatory cytokines (TNF-α, IL-1β, and IL-6) and neutrophils were the highest on day 3 of infection." (PMID 36982713, 2023). "A previous study found that cell wall-associated lipids of N. brasiliensis promoted IL-6 production by macrophages and inhibited TNF-α production by macrophages during infection." (PMID 36926518, 2023). "C57BL/6, CD-1, and BALB/C mice have an increase in IL-6 production post-infection with B. pertussis." (PMID 37917623, 2023). "Levels of interferon-gamma (IFNγ), TNF and interleukin 6 (IL-6) similarly peaked in BALF of control mice 5 days after infection, and were likewise decreased and delayed in Gabra1-IRES-cre; Ptger3flox mice." (PMID 36890237, 2023). "TGF β1 was the best biomarker of severity during the early phase of infection (AUC: 0.99), followed by IL-10 (AUC: 0.99), IL-6 (AUC: 0.82), and IL-17 (AUC: 0.71)." (PMID 37569646, 2023). "IL-6 plays a vital role in infection-induced cytokine storm and acute lung injury, which is a molecular marker of the severity of acute lung injury." (PMID 36902060, 2023).
infection (continued). "AhR deficiency in mice revealed increased production of pro-inflammatory cytokines (e.g., IL-6 and TNF-α) by macrophages after infection, resulting in higher susceptibility to L. monocytogenes, with higher morbidity and mortality rates." (PMID 36672703, 2023). "We showed that BMDCs from an early stage of AE infection expressed high levels of IL-6 and TGF-β, while IL-10 and TNF-α gene expression levels were persistently low in concordance with previous reports." (PMID 37888588, 2023). "Clearance of these bacteria from the breast relies on a rapid and strong innate immune response, including the secretion of cytokines such as IL-1β and IL-6 and chemokines such as IL-8, which attract neutrophils to the site of infection." (PMID 38003112, 2023). "Upon inhibition of p38, the expression of all three cytokines was significantly reduced (p < 0.05), except for IL-6 expression in the B1033C infection group (p > 0.05)." (PMID 37998345, 2023). "In our global correlation analyses, neutrophils were also positively correlated with the inflammatory cytokine IL-6, and all of these immune parameters were positively correlated with severe infection." (PMID 37598150, 2023). "Infection with bacteria activates pro-inflammatory gene programs, such as expressing the IL-1β, IL-6, and tumor necrosis factor genes through transcription factors." (PMID 37958634, 2023). "During infection, the lungs employ physical barriers and immune cells that release inflammatory cytokines like IL-6, IL-1β, and IL-18, initiating the inflammatory response." (PMID 37686825, 2023). "By secreting chemokines such as IL-8, epithelial cells direct immune cells to sites of infection and simultaneously secrete other cytokines IL-6 and IL-1β to activate inflammatory immune responses of both the innate and adaptive immune systems." (PMID 37240735, 2023). "Inflammatory mediators including IL1β, TNF, and IL6 displayed significant differential secretion across the time points, indicating their contribution to a pro-inflammatory reaction to infection." (PMID 37333188, 2023). "The justification for the choice is that in the early stage of severe infection, numerous inflammatory factors, mainly IL-6, are released, leading to proinflammatory reactions." (PMID 37310657, 2023). "Blood and peritoneal lavage fluid samples were then taken at 24- and 48-h post infection and subjected to ELISA analysis using either IL-6 or MCP-1 antibody." (PMID 36937293, 2023). "Interleukin-6: Interleukin-6 (IL-6) is a pro-inflammatory cytokine produced by various cells, including macrophages and endothelial cells, in response to infection or inflammation." (PMID 37510130, 2023). "In infections with regular vegetative cells, the IL-6 and TNF-α inflammatory response continued to increase in the first 1.5 h, remaining constant at 24 h, while CXCL-8 decreased by 24 h." (PMID 36920189, 2023). "Serum levels of IgA and cytokines (IFN-γ, IL-4 and IL-6) were significantly elevated in infected unprotected group II when compared to healthy control group I on days 3, 7 and 14 after infection." (PMID 37943403, 2023). "Innate lymphoid cells (ILCs) predominantly produce IL-22 during the early stages of infection through an IL-23-dependent pathway, whereas CD4+ T cells secrete IL-22 during the later stages of infection via an IL-6-dependent pathway." (PMID 37646028, 2023). "Observation of abdominal incisions showed that surgical wound in the MSCs and control groups were healing better and less infection than that of the IL-6-AB group." (PMID 36895785, 2023). "Upregulation of AAT occurs in response to infection and tissue injury, in order to promote tissue repair, in a mechanism driven by interleukin-6 (IL-6) and tumor necrosis factor (TNF)." (PMID 36983294, 2023). "Specifically, IL-6, which is commonly used as a marker of infection, showed significantly higher levels in septic samples, as expected." (PMID 37240374, 2023).
infection (continued). "Overall, there was not a statistically significant interaction between postnatal age and infection status for IL-6 (p = 0.08), but a significant interaction was present for CRP (p < 0.001)." (PMID 37606448, 2023). "Treatment with rL. lactis prior to infection with C. perfringens led to a time- and site-specific dependent increase in expression of IL-6, and IL-8." (PMID 38164397, 2023). "Firstly, DMI maintained the homeostasis of inflammation by reducing the level of proinflammatory (Il6 and Il1b) and anti-inflammatory (Il10) cytokines in vivo and in macrophages during infection." (PMID 36882813, 2023). "Higher viral loads were observed in the serum and brains of IL-6−/− mice at different time points of the infection." (PMID 38053527, 2023). "The livers of C57BL/6 mice inoculated with 10,000 SPZ of either IL-6 Tg-PbANKA/LISP2 or WT PbANKA parasites were harvested at 48h post-infection and were subjected to RT-qPCR using primers designed to detect the codon-optimized parasite-encoded IL-6 transgene." (PMID 37143657, 2023). "As expected, proinflammatory cytokines, such as IL-6, IL-8, and IL-1α, as well as the antimicrobial peptide hBD-2 are upregulated upon infection with M. furfur." (PMID 36835509, 2023). "The pathophysiology of infection and inflammation suggested the deep involvement of cytokines, including IL-6, in the abnormal serum lipid profile." (PMID 37371970, 2023). "—Mixed LAB strains from wild pigs exerted a beneficial effect on the host via immunomodulation of IL-6 and IL-1b against the infection of E. coli." (PMID 36387374, 2022). "IL-6 is a potent pro-inflammatory cytokine which is crucial for a rapid and coordinated immune response during infections and tissue injuries, but also helps to maintain the hematopoietic system." (PMID 36248849, 2022). "Although APPs are predominantly expressed by hepatocytes to be secreted into the blood, they can also be produced by endothelial cells and leukocytes activated by pro-inflammatory cytokines (e.g., IL1B and IL6) at the site of infection." (PMID 35401509, 2022). "Patients in the low Sirt3 group had higher ScvO2, lactate, APACHE II score, SOFA score, longer ICU stays, and worse indicators of inflammation (TNF-α, IL-6) and infection (PCT) than those in the high Sirt3 group (P < 0.05)." (PMID 35729330, 2022). "IL-6 is a pro-inflammatory cytokine that is produced when inflammation, infection, and tumors occur." (PMID 35765486, 2022). "Our results show that IL-6 from B cells is an important factor for local Tfh formation and IL-21 production during the early phase of infection." (PMID 35154093, 2022). "Inhibition of miR-223-3p did not impact levels of CCL2, IFN-stimulated gene 15 (ISG15), or IL-6 in either SARS-CoV-WT or ΔE infection at any time point." (PMID 35229638, 2022). "TNF-α (≥10 pg/mL) detected in infections by 75% of isolates, IL-6 (≥80 pg/mL) by 30% of isolates and low levels of NO (≥0.01μM) in almost all infections." (PMID 35531337, 2022). "SARS-CoV-2 D614G- and Delta- variant infection induced production of inflammatory cytokines, including high-level of IL-2, GM-CSF, KC at day 3 pi and IL-1β, TNF-α, IL-2, IL-4, IL-6, KC (Neutrophil chemoattractant) at day 7 pi." (PMID 35734088, 2022). "Meanwhile, the infection cytokines IL-6 expression in plasma were augmented in the ALI groups (p < 0.0001) compared to Control group." (PMID 36266722, 2022). "Under the stimulus of the 501Y.V2/B.1.35 strain infection, the expression of IL-6, IL-8, IP-10, CCL-5, MIP-1α significantly increased after infection for 48 h compared with NC group (P < 0.001 or P < 0.01)." (PMID 35365215, 2022). "CRP is an acute phase reaction protein that is released primarily from hepatocytes in response to increased concentrations of interleukin (IL)-6 and is elevated during tissue damage, infection, and inflammation." (PMID 35060938, 2022).
infection (continued). "Another study showed that F. nucleatum significantly promoted the secretion of TNF-α and IL-1β, while S. gordonii promoted the secretion of TNF-α, IL-6, IL-8, and IL-1β after 24 h of infection." (PMID 35573793, 2022). "This resulted in a roughly twofold increase in TNF and several‐fold increase in IL‐6 release by MDMs after infection with TIGR4Δply compared to TIGR4." (PMID 35835695, 2022). "We did not detect a significant increase in the secretion of either cytokines in cells infected with the T3SS and T6SS mutants, suggesting that both of these virulence systems play a role in triggering IL-6 and IL-8 production during infection." (PMID 35508983, 2022). "Studies have also shown that WPM containing transition metals significantly increases the levels of several types of infection-related cytokines, such as IL-1β and IL-6, in the airway epithelium, resulting in airway wall collapse." (PMID 35837279, 2022). "In order to confirm the role of αvβ3 integrin in the production of IL-6 and IL-8 after infection with HAdV26 we measured the amounts of those cytokines at 6 h and 24 h p.i. in SK-OV-3 cells transfected with β3 integrin-specific siRNA, si(β3)_2." (PMID 35458402, 2022). "The mRNA levels of the inflammatory factors, namely IL-1β, IL-6, and IL-8, increased gradually with the extended infection time." (PMID 36311798, 2022). "IL-6 is one of the key cytokines involved in the infection-induced cytokine storm and CAR-T cell therapy-induced CRS." (PMID 35757715, 2022). "In response to an infection, the body releases Interleukin-6 (IL-6) and other proinflammatory cytokines." (PMID 36012562, 2022). "Unexpectedly, in rats, we did not observe significant activation of Th1 cytokines in the acute infection phase of AC (1 dpi), while the level of the Th2 cytokine IL-6 was obviously increased." (PMID 35617354, 2022). "In cGAS knockdown cells, we observed that, although viral RNA levels were unchanged, there was a significant decrease in TNF and IL-6 mRNA transcript levels following infection." (PMID 35022513, 2022). "TNF-α, IL-1, and IL-6 are pro-inflammatory cytokines essential for initiating an inflammatory response to infection." (PMID 35356501, 2022). "Under the stimulus of the G/478 K.V1/ B.1.617.2 strain infection, the mRNA expression of IL-6, IP-10, CCL-5 and IL-1α significantly was increased after infection for 48 h compared with NC group (P < 0.001)." (PMID 35365215, 2022). "After PEDV-HBQY2016 strain infection, the expression levels of IL-1β, IL-6, MIP-1β, MCP-1, IL-8 and CXCL10 were significantly higher than those in in the control group." (PMID 36439802, 2022). "Infection by SARS-CoV-2 induces a dose-dependent production of IL-6 from bronchial epithelial cells." (PMID 36503381, 2022). "Its role as a major mediator of the acute phase response to infection or tissue injury further justified the choice of IL-6 as the marker of inflammation." (PMID 35345614, 2022). "Following infection with opportunistic pathogens, cytokine expression of IL-1β, IL-6, and TNF-α in the mucosa and serum increased significantly (P < 0.05), which resulted in decreased immunity." (PMID 35769317, 2022). "When homeostasis is disturbed after infection or tissue damage, IL-6 is instantly produced to assist the host's defense against such stress by stimulating acute-phase and immunological responses." (PMID 36518854, 2022). "During infection, inflammatory mediators increased in both cohorts, reaching significance only for IL-6 in controls (p=0.047)." (PMID 36466839, 2022). "PhiMR003 did not change the number of inflammatory cells in the infiltrate during KYMR58 infection, even though IL-1β and IL-6 levels significantly decreased." (PMID 36123529, 2022). "With GAPDH normalization, even asymptomatic patients exhibited significant induction of IL-6, and the IL-6 expression was also comparable with that of patients having moderate infections and those with CAM." (PMID 36377893, 2022).